ATM (ATM serine/threonine kinase)
Diseases named in the same sentence as ATM in open-access papers (continued):
Sharing a sentence is not in itself a finding about the gene and the disease.
lung adenocarcinoma (continued). "The ATM-dependent DNA damage response pathway is frequently altered in NSCLC, with ATM mutations reported in approximately 9% of lung adenocarcinomas (LUAD) and 4% of squamous cell carcinomas, leading to genomic instability and enhanced tumor survival under genotoxic stress." (PMID 41301482, 2025). "Additionally, these studies demonstrate that germline variants in ATM are one of the most frequent germline alterations in lung adenocarcinoma." (PMID 38539485, 2024). "Similarly, germline ATM variants have been strongly associated with moderate penetrance in catalyzing lung adenocarcinoma." (PMID 38539485, 2024). "PLF can enhance the cytotoxicity of heavy ion irradiation on lung adenocarcinoma (A549) cells and reduce the phosphorylation of the ataxia telangiectasia-mutated (ATM)-dependent pathway checkpoints during DNA damage, and combination therapy can also reduce tumor volume." (PMID 38202798, 2023). "A related compound, VE-822, markedly increased the sensitivity of ATM-deficient lung adenocarcinoma cells leading the authors to propose that ATM deficiency could be useful as a marker for ATR and PARP sensitivity." (PMID 32784607, 2020). "It has been reported that that PD-L1 is associated with EMT transition in adenocarcinoma of lung and in head and neck squamous cell carcinoma respectively, we hypothesis that PD-L1 may play a role in mediated ATM/EMT pathway in cisplatin-resistant NSCLC cells." (PMID 30961670, 2019). "This could improve clinical outcome in 100,000's of patients with ATM-deficient lung adenocarcinoma every year." (PMID 27259260, 2016). "ATM is a tumor suppressor often mutated in lung adenocarcinoma." (PMID 27922010, 2016). "Somatic mutations in ATM were identified previously in 14 of 188 lung adenocarcinomas (7 %)." (PMID 26438152, 2015). "Somatic mutations in ATM have been identified previously in 14 of 188 lung adenocarcinomas (7 %)." (PMID 26438152, 2015). "Moreover, loss of ATM protein expression has been reported in over 40% of lung adenocarcinomas." (PMID 38807759, 2024). "To empirically test whether olaparib can target ATM-deficient human cell lines, we used CRISPR/Cas9 to deplete ATM and DNA-PKcs from A549 cells, a human lung adenocarcinoma cell line, and used these cells to interrogate the mechanism by which lung adenocarcinoma cells respond to olaparib." (PMID 31481733, 2019). "Thus, up to 7 % of lung adenocarcinomas that have acquired somatic mutations that inactivate ATM may respond to single agent therapy with an ATR kinase inhibitor." (PMID 26438152, 2015). "In addition, other SNPs in ATM gene and in this pathway may be involved in the risk of lung adenocarcinoma, gene-gene interaction and haplotypes may offer more clues to clarity the association between host genetic susceptibility and lung adenocarcinoma risk." (PMID 24819391, 2014). "It was also found that ATM defective lung adenocarcinoma is sensitive to cisplatin and olaparib, as a result of incompetent homologous recombination repair." (PMID 36233063, 2022). "The ATM expression at the transcriptional and translational levels in human lung adenocarcinoma A549 and H460 cells were detected by PCR and western blot." (PMID 34055781, 2021). "Somatic mutations of multiple MMR genes as well as POLE, POLQ, ATM, and ATR were significantly associated with higher neoantigen loads in UCEC, BRCA, lung adenocarcinoma (LUAD), and STAD (FDR < 1.2 × 10−5)." (PMID 34095878, 2021). "We deleted ATM from A549 lung adenocarcinoma cells using CRISPR/Cas9 and determined the effects of olaparib and the ATM/Rad3-related (ATR) inhibitor VE-821 on cell viability." (PMID 31481733, 2019). "IC50 values for both olaparib and talazoparib positively correlated with ATM mRNA levels and gene amplification status in lung adenocarcinoma cell lines." (PMID 31481733, 2019).
lung adenocarcinoma (continued). "Based on these data, we deleted either ATM or the related protein kinase DNA-PKcs/PRKDC from A549 lung adenocarcinoma cell lines using CRISPR/Cas9, and used these cells to examine the mechanism of action of olaparib." (PMID 31481733, 2019). "Lung adenocarcinoma patients with WSE showed a distinctive mutated profile for the SMARCB1, ATM, EGFR exon 7, RET and KDR genes." (PMID 30093964, 2018). "In the present study, we compared the effects of LDR on A549 lung adenocarcinoma cells and HBE135-E6E7 (HBE) normal lung epithelial cells with the focus on ATM and its associated signaling pathways." (PMID 27708248, 2016). "A tissue microarray (TMA) of lung adenocarcinomas obtained from the the University of Pittsburgh Lung Specialized Program of Research Excellence (SPORE) was stained for ATM at the Biomarker Division of AstraZeneca in Cambridge, UK." (PMID 27259260, 2016). "In large-scale genomics efforts, ATM coding sequence alterations were identified in ≤12% lung adenocarcinoma." (PMID 27259260, 2016). "The effect of metformin was tested on the level of constitutive expression of γH2AX and Ser1981-phoshorylated ATM in human lung adenocarcinoma A549 cells." (PMID 22067284, 2011). "However, another study that compared the rate of prevalence of BRCA1 and BRCA2 PGVs in patients with lung adenocarcinoma with ATM PGVs reported a higher prevalence of BRCA1 and BRCA2 PGVs." (PMID 38539485, 2024). "Mutations in EGFR, ATM, and PIK3CA may provide new ideas for predicting TMB in lung adenocarcinoma patients." (PMID 35521981, 2022). "Interestingly, ATM/ATR was induced more strongly by γ-rays at 1 Gy than by C-ions (LET 290 keV/μm) at 4 h post-irradiation in lung adenocarcinoma A549 cells." (PMID 34681703, 2021). "For lung adenocarcinoma and endometrial carcinoma, we observed a cross-cancer effect for KRAS/NRAS-mutated cases as ATM levels are decreased, and MAPK_pT202_Y204, Claudin-7, S6_pS235_S236, and MEK1_pS217_S221 are increased in both histological tumor types consistently." (PMID 30442178, 2018). "Thus, the available data suggest that a yet to be identified mechanism controls either the translation or degradation of ATM protein in lung adenocarcinoma." (PMID 27259260, 2016). "Furthermore, three genes were among the top 20 most frequently mutated genes in lung adenocarcinoma: EGFR (34%), ATM (5%) and KDR (5%)." (PMID 24646369, 2014). "This study aimed to investigate the association between the ATM -111G>A (rs189037) polymorphism, environmental risk factors and the risk of lung adenocarcinoma in Chinese female non-smokers." (PMID 24819391, 2014). "But it is noteworthy that our study investigated the association between ATM rs189037 polymorphism and lung adenocarcinoma risk in a non-smoking females population for the first time." (PMID 24819391, 2014). "To date, the association between ATM rs189037 and host susceptibility to lung adenocarcinoma in Chinese female non-smokers has not been well addressed." (PMID 24819391, 2014). "The results of this study demonstrate that ATM‐ and PIK3CA‐positive and EGFR‐negative mutation status are strongly associated with high levels of TMB and have the potential to be predictive biomarkers of response to immune checkpoint inhibitors in lung adenocarcinoma patients." (PMID 35521981, 2022). "We hypothesize that carcinogens released by WSE produce frameshift truncations, resulting in loss of protein function in the tumor suppressors ATM and SMARCB1, and subsequent mutations in the oncogenes RET, KDR and EGFR exon 7 among others involved in the development of lung adenocarcinoma." (PMID 30093964, 2018).
lung adenocarcinoma (continued). "ATM rs189037 might be associated with the risk of lung adenocarcinoma in Chinese non-smoking females." (PMID 24819391, 2014). "According to the results above, we assumed that ATM rs189037 AA genotype might affect lung adenocarcinoma risk among non-smoking Chinese females." (PMID 24819391, 2014). "In summary, this hospital-based case-control study showed that ATM rs189037 might be associated with the risk of lung adenocarcinoma in Chinese non-smoking females." (PMID 24819391, 2014). "Although no specific ATM genotype-phenotype correlations were discerned in this study, we did observe that the ATM c.1564_1565delGA variant was present in two patients with uterine cancer, and the ATM p.V2716A variant was present in two patients with lung adenocarcinoma." (PMID 36865800, 2023). "On this study we describe a landscape of genomic alterations in lung adenocarcinoma patients with WSE in the tumor suppressors SMARCB1 and ATM, in addition to the oncogenes EGFR, RET and KDR." (PMID 30093964, 2018). "Furthermore, ATM rs189037 AA genotype might be a risk factor of lung adenocarcinoma among female non-smokers without cooking oil fume exposure." (PMID 24819391, 2014). "Furthermore, ATM rs189037 AA genotype might be a risk factor affecting lung adenocarcinoma among females without cooking oil fume exposure." (PMID 24819391, 2014). "However, low- and high-LET irradiation elicit quite different DDRs: for instance, in lung adenocarcinoma A549 cells, C-ions (LET 290 keV/μm) at 1 Gy induced ATM/ATR activation more strongly than γ-rays at 4 h post-irradiation." (PMID 34681703, 2021). "This is consistent with the fact that ATM mutations represent an early event in NSCLC pathogenesis and over 40% of lung adenocarcinomas are negative for ATM protein expression." (PMID 30093964, 2018). "Overall, 61 (41%, 95% confidence interval 34%-50%) of lung adenocarcinomas were ATM negative and 86 (59%, 95% confidence interval 50%-66%) were ATM positive." (PMID 27259260, 2016). "We show here that 61 of 147 (41%) of lung adenocarcinomas have been demonstrated to be negative for ATM protein expression." (PMID 27259260, 2016). "Here we report the validation of a commercial antibody (ab32420) for the identification of ATM by immunohistochemistry and estimate that 61 of 147 (41%, 95% CI 34%-50%) cases of lung adenocarcinoma are negative for ATM protein expression." (PMID 27259260, 2016). "Remarkably we show that 61 of 149 (41%) lung adenocarcinomas can be considered negative for ATM protein expression." (PMID 27259260, 2016). "Our finding that 61 of 147 (41%) of lung adenocarcinomas are ATM negative suggests that combinations of an ATR kinase inhibitor with standard-of-care cisplatin may improve clinical outcome in 100,000's of patients with ATM-deficient lung adenocarcinoma every year." (PMID 27259260, 2016).
breast tumors (47 papers, 2004 to 2026). "They demonstrate that a mutated PTEN cannot undergo phosphorylation by ATM, which accelerates tumorigenesis in Her2+ breast tumors." (PMID 40259910, 2025). "We identified the combined inhibition of EZH2 and the proximal DNA damage response kinase ATM as a novel synthetic lethality-based therapy for the treatment of BRCA1-deficient breast tumors." (PMID 35715861, 2022). "CDK12 promotes migration and invasion of HER2-positive breast tumor cells through regulating the ALE splicing of DDR activator ATM (ataxia telangiectasia-mutated) and DNAJB6 (DnaJ homolog subfamily B member 6, MRJ)-L." (PMID 32570740, 2020). "Among the 41 reviewed ATM-associated breast tumours, 36 were invasive carcinomas and 5 were in situ carcinomas." (PMID 29665859, 2018). "Whole-genome massively parallel sequencing of four ATM-associated breast tumours (T0001-L, T0015-L, T0077-L and T0077-R) and their respective germline DNA was used to characterise the genetic landscape of ATM-associated tumours at base pair resolution." (PMID 29665859, 2018). "Copy number losses at 16q, 17p and 22q, which are known features of breast tumours of the luminal A and B subtypes, were also seen in 70% of ATM-associated tumours." (PMID 29665859, 2018). "ATM-associated breast tumours were mostly luminal B (46%) and luminal A (36%), and the distribution of the molecular subtypes differed significantly from that of the PICBIM series." (PMID 29665859, 2018). "The study revealed that most ATM-associated breast tumours are luminal B or luminal B/HER2+ tumours, which is consistent with a recent case-control study showing that ATM TV carriers are at increased risk of developing ER+ breast tumours." (PMID 29665859, 2018). "So far, no clear histopathological and molecular features have been described for ATM-associated breast tumours (i.e., tumours developed by subjects carrying one or two mutated copies of ATM), and well-documented ATM tumour series are very limited." (PMID 29665859, 2018). "Genome-wide profiling of the 23 ATM-associated tumours revealed multiple copy number aberrations, including those previously reported in breast tumours, such as losses at 8p and gains at 8q, occurring in 50% and 70% of ATM-associated tumours, respectively." (PMID 29665859, 2018). "Two breast tumors demonstrated two distinct ATM variants that were classified as potential causal missense mutations, but several breast tumors and controls displayed multiple ATM variants classified as polymorphisms." (PMID 25625042, 2015). "Deletions at 11 q have been described previously in association with BRCA2 breast tumors wherein aberrant expression of ATM has been demonstrated." (PMID 21958427, 2011). "Similarly, breast tumors with ATM PVs lack HRD-related mutational signatures, in line with our functional classification of sample BC-26 with an ATM PV as HRP." (PMID 37725154, 2023). "In addition, other cancer types in this family have been associated with ATM mutations such as thyroid, ovarian and breast tumours." (PMID 32756499, 2020). "Also, mechanistic studies show that miR-18a has an important role in downregulating ATM (Ataxia Telangiectasia Mutated), a DNA repair protein, in breast tumor tissues." (PMID 31191653, 2019). "We thus determined whether induction of ATM-associated DNA damage is the main trigger for SALL1-induced senescence in breast tumor cells." (PMID 29625565, 2018). "This exploratory study in which we investigated both the histological and molecular features of breast tumours developed by subjects who inherited one or two mutated copies of ATM describes, to our knowledge, the largest series of ATM-associated tumours reported to date." (PMID 29665859, 2018).
breast tumors (continued). "Moreover, all ATM-associated breast tumours and the control series were blindly reviewed by trained reference pathologists of Institut Curie (AVS and GB), thus ensuring unbiased scoring of the morphological features." (PMID 29665859, 2018). "Interestingly, tumour genomic profiling revealed that ~ 70% of ATM-associated breast tumours are tetraploid." (PMID 29665859, 2018). "Finally, to complete the repertoire of somatic alterations of ATM-associated breast tumours, we performed whole-genome sequencing (WGS) on four tumours from HetAT participants with available frozen material." (PMID 29665859, 2018). "This may explain the prevalence of Her2+ breast tumors in patients with mutated ATM." (PMID 40259910, 2025). "ATM is required for three cell cycle checkpoints- G1/S border, S phase and G2/M- after DNA double-strand breaks, so the emergence of polyploidy could be due to cell cycle checkpoint defects linked to inactivation of ATM in breast tumours." (PMID 29665859, 2018). "Here, we found that MRE11 is deacetylated by the SIRT2 sirtuin deacetylase and breast tumor suppressor, which promotes DNA binding to facilitate DNA end resection and ATM-dependent signaling." (PMID 41505211, 2026). "This study reveals distinct patterns in the molecular profiles of breast tumors linked to mutations in BRCA1, BRCA2 and ATM." (PMID 40259910, 2025). "Overall, our study identified 19 ATM mutation carriers with 24 breast tumors and 17 CHEK2 mutation carriers with 22 breast tumors." (PMID 33919281, 2021). "Each inhibitor was studied in MCF7 breast tumor cells over a range that included concentrations previously shown to be pharmacologically active (10 μM KU55933 [ATM], 0.4 μM rucaparib [PARP], and 1 μM VE-821 [ATR])." (PMID 31581151, 2020). "It has been shown that triple-negative and HER2+ primary breast tumors exhibited higher frequency of expression of γH2AX, a component in the ATM/H2AX DNA damage response complex that facilitates the DNA damage repair." (PMID 30746635, 2019). "As expected, in our series, lower levels of both BRCA1 and ATM genes were observed in sporadic breast tumors in which higher expression of TGFB1 was observed." (PMID 28881597, 2017). "Using PCR-Single Strand Conformation Polymorphism (SSCP) analysis and direct DNA sequencing, we screened a panel of 100 consecutive, unselected sporadic breast tumors and 100 matched controls for all 62 coding exons and flanking introns of the ATM gene." (PMID 25625042, 2015). "There has been a high frequency of DNA methylation observed in advanced breast tumors and attributed to reduced ATM expression and function." (PMID 25625042, 2015). "MRE11, a breast tumor suppressor and component of the MRE11-RAD50-NBS1 complex, plays a critical role in DNA end resection and initiation of ataxia-telangiectasia mutation-dependent (ATM-dependent) DNA damage signaling." (PMID 41505211, 2026). "Future work will also include in vivo validation using xenograft or orthotopic breast tumor models to assess whether combinational ATM and Topo-II inhibition can achieve selective tumor killing without affecting normal tissue." (PMID 41557625, 2026). "Moreover, tetraploidy, loss of the wild-type allele at the ATM locus, and copy number loss/LOH at loci 13q14.11-q14.3, 17p13.2-p12, 21p11.2-p11.1 and 22q11.23 are hallmarks of breast tumours developed by ATM variant carriers." (PMID 29665859, 2018).